TRPC3 (transient receptor potential cation channel subfamily C member 3)
Diseases named in the same sentence as TRPC3 in open-access papers (continued):
Sharing a sentence is not in itself a finding about the gene and the disease.
chronic pancreatitis (1 paper, 2017). A chronic inflammatory process causing damage and fibrosis of the pancreatic parenchyma. "Data mining of published microarray analyses of microdissected patient tissue samples revealed that TRPC3 channels are upregulated in the stromal compartment of PDAC as compared to that of chronic pancreatitis." (PMID 27903970, 2017).
COVID-19 (1 paper, 2022). A disease caused by infection with severe acute respiratory syndrome coronavirus 2. "We demonstrate that targeting inhibition of TRPC3-Nox2 complex is a new strategy for the prevention of cardiac severity after COVID-19." (PMID 36613540, 2022). "In addition to S protein exposure, exposure to chemical stresses considered as risk factors for severe COVID-19 also induces ATP release, and the released ATP increases ACE2 expression through TRPC3-Nox2 complex formation." (PMID 36613540, 2022). "Epidemiologically reported risk factors of severe COVID-19, including cigarette sidestream smoke (CSS) and anti-cancer drug treatment, commonly upregulate ACE2 expression level, and these were suppressed by inhibiting TRPC3-Nox2 complex formation." (PMID 36613540, 2022).
cystitis (1 paper, 2025). Inflammation of the urinary bladder. "Our study found that both mRNA and protein expression levels of TRPC3 are upregulated in the bladder of CYP-induced cystitis rats." (PMID 40271070, 2025). "Significant findings revealed TRPC3 RNA and protein expression was markedly upregulated in cystitis rats." (PMID 40271070, 2025). "Of these, TRPC3 emerged as the most highly upregulated gene in CYP-induced cystitis rats compared to normal rats." (PMID 40271070, 2025). "TRPC3 is predominantly expressed in fibroblasts and fibrosis-related pathways are upregulated in cystitis rats." (PMID 40271070, 2025). "Western blot studies confirmed a substantial increase in TRPC3 expression in the bladders of CYP-induced cystitis rats, corroborating the findings from our bioinformatics analysis." (PMID 40271070, 2025). "Initial findings confirmed that Pyr3 effectively inhibits the overexpression of TRPC3 in the bladders of CYP-induced cystitis rats (P < 0.05)." (PMID 40271070, 2025). "To investigate the role of TRPC3 in bladder fibrosis, we administered Pyr3, a selective TRPC3 inhibitor, to CYP-induced cystitis rats." (PMID 40271070, 2025).
Duchenne muscular dystrophy (1 paper, 2025). Duchenne muscular dystrophy (DMD) is a neuromuscular disease characterized by rapidly progressive muscle weakness and wasting due to degeneration of skeletal, smooth and cardiac muscle. "In skeletal muscle from sciatic nerve transection model mice and Duchenne muscular dystrophy (mdx) mice, TRPC3-Nox2 complex formation was enhanced." (PMID 41596097, 2025).
edema (1 paper, 2024). An abnormal accumulation of fluid beneath the skin, or in one or more cavities of the body. "After intraperitoneal injection of a TRPC3 agonist, the general condition, growth state, and lung development in the BPD + group significantly improved compared with the BPD group, but pulmonary edema and a small amount of inflammatory cell infiltration remained." (PMID 40625902, 2024).
energy (1 paper, 2024). "Furthermore, knockdown or knockout (KO) of Trpc3 in mice ameliorated D-gal-induced mitochondrial reactive oxygen species production, membrane potential deterioration, and energy metabolism disorder." (PMID 38415902, 2024).
Hearing impairment (1 paper, 2012). A decreased magnitude of the sensory perception of sound. "Double TRPC3/TRPC6 knock-out mice also showed hearing impairment, vestibular deficits and defective auditory brain stem responses to high-frequency sounds." (PMID 22724068, 2012).
Hepatic steatosis (1 paper, 2024). Steatosis is a term used to denote lipid accumulation within hepatocytes. "TRPC3 loss robustly aggravated the alcohol-induced hepatic steatosis and liver injury in mouse liver; this was associated with the suppression of Ca2+/calmodulin-dependent protein kinase kinase 2 (CAMKK2)/AMP-activated protein kinase (AMPK) and dysregulation of genes related to lipid metabolism." (PMID 39871879, 2024). "Liver-specific TRPC3 silencing aggravates alcohol-induced hepatic steatosis and liver injury by suppressing Ca2+/calmodulin-dependent protein kinase kinase 2 (CAMKK2)/AMPK signaling pathway." (PMID 39871879, 2024). "Mice with liver-specific TRPC3 silencing manifested mild fatty liver and exacerbated liver pathologies of ALD upon chronic alcohol consumption, whereas genetic replenishment of hepatic TRPC3 ameliorated ALD development." (PMID 39871879, 2024). "Having established that TRPC3 deficiency is causally linked to alcohol-associated hepatic steatosis, we further explored whether overexpression of TRPC3 is sufficient to improve alcohol-induced hepatic steatosis in mice." (PMID 39871879, 2024). "In an attempt to explore the mechanism by which TRPC3 knockdown aggravated hepatic steatosis in ALD, our data uncovered that TRPC3 deficiency was associated with AMPK suppression in mouse liver, evidenced by decreased protein abundance of p-AMPK and its down-stream target, p-ACC." (PMID 39871879, 2024). "However, endothelial-specific TRPC3 overexpression aggravated high-fat diet-induced hepatic steatosis compared with that in littermate controls." (PMID 39871879, 2024). "A recent study has reported that globally depleting TRPC3 neither attenuated nor worsened liver steatosis induced by choline-deficient, L-amino acid-defined, and high-fat diet." (PMID 39871879, 2024).
Hyperkalemia (1 paper, 2014). An abnormally increased potassium concentration in the blood. "Our recent attempt in exploring the impact of hyperkalemia on endothelial Ca2+ channels provided the first evidence of the alteration of TRPC3 channels and the functional significance of TRPC3 alteration in hyperkalemia-induced EDHF dysfunction." (PMID 25126553, 2014).
injury (1 paper, 2020). Damage inflicted on the body as the direct or indirect result of an external force, with or without disruption of structural continuity. "Transient receptor potential canonical (TRPC) channels, especially TRPC3/6, were proposed to be essential therapeutic targets for kidney injury." (PMID 32719603, 2020).
Interstitial cardiac fibrosis (1 paper, 2019). A type of myocardial fibrosis characterized by excessive diffuse collagen accumulation concentrated in interstitial spaces. "Recently, chronic treatment of rat models of pressure overload with GSK503A, proposed to inhibit both TRPC3 and TRPC6, showed no interstitial cardiac fibrosis, suggesting that TRPC3 and TRPC6 are needed for the fibrosis appearance." (PMID 30881310, 2019).
keloid (1 paper, 2024). An irregularly shaped, elevated mark on the skin caused by deposits of excessive amounts of collagen during wound healing. "For instance, obesity has been implicated in the formation of scar keloids, and high salt intake is also associated with hypertrophic scar formation through mechanisms involving TRPC3-mediated mitochondrial Ca2+ homeostasis dysfunction." (PMID 39114830, 2024).
leukaemia (1 paper, 2021). "In this regard, integrated methylome, transcriptome, and epigenetic analysis showed that the expression level of many genes is dysregulated in paediatric leukaemia, and among them, the presence of TRPC1, TRPC4, TRPC3, TRPM2, TRPM4, and TRPM8 also stands out." (PMID 34065398, 2021).
lung squamous cell carcinoma (1 paper, 2013). "In lung squamous cell carcinoma sections, the squamous cells were strongly stained with anti-TRPC1, anti-TRPC3, anti-TRPC4 and anti-TRPC6 antibodies." (PMID 23840757, 2013).
malaria (1 paper, 2020). Malaria is a serious and sometimes fatal disease caused by a parasite that commonly infects a certain type of mosquito which feeds on humans. "Considering that the plasma concentrations of artemisinin reached in malaria treatment typically do not exceed 1 μM, the effect of the drug on TRPC3 is presumably not related to its antiplasmodial activity, and vice versa." (PMID 31947602, 2020).
malignant glioma (1 paper, 2021). A grade III or grade IV glioma arising from the central nervous system. "Furthermore, TRPC3 expression in human malignant gliomas was reported to be in the same range with that of normal brain tissues." (PMID 34946686, 2021).
myelofibrosis (1 paper, 2021). A partial or complete replacement of the bone marrow stroma by fibrous tissue. "Nonetheless, early reports demonstrated that extracellular Ca2+ entry through two distinct DAG‐sensitive pathways, that is TRPC1 and TRPC3, induced intracellular Ca2+ oscillations, respectively, in primary myelofibrosis‐derived ECFCs21 and UCB‐derived ECFCs." (PMID 34288391, 2021).
nutritional deficiency (1 paper, 2019). "Limitations of study: our current study uncovers a new pathway in the development of cardiomyocyte atrophy, where TRPC3-Nox2 axis, activated by extracellular ATP, mainly contributes to nutritional deficiency-induced atrophy through ROS production." (PMID 31278358, 2019). "Lastly, atrophy of cardiomyocyte and extracellular release of ATP were observed in nutritional deficiency, which were dependent on TRPC3 and Nox2." (PMID 31278358, 2019). "Strikingly, knockdown of either TRPC3 or Nox2 suppressed nutritional deficiency-induced ATP release, as well as ROS production and NRCM atrophy." (PMID 31278358, 2019). "Taken together, we propose that TRPC3-Nox2 axis, activated by extracellular ATP, is the key component that mediates nutritional deficiency-induced cardiomyocyte atrophy." (PMID 31278358, 2019). "Here, we show that high level of extracellular ATP, which is induced by nutritional deficiency, mediates atrophy in neonatal rat cardiomyocytes (NRCMs), via formation of TRPC3-Nox2 complex." (PMID 31278358, 2019).
osteoporosis (1 paper, 2024). A condition of reduced bone mass, with decreased cortical thickness and a decrease in the number and size of the trabeculae of cancellous bone (but normal chemical composition), resulting in increased fracture incidence. "TRPC3 and TRPC6 are associated with osteoporosis, with TRPC3 promoting osteoclast differentiation and bone resorption in TRPC6-deficient phenotypes." (PMID 39170742, 2024). "Additionally, TRPC3 has been found to be highly expressed in individuals with reduced bone mass, suggesting that TRPC3 may serve as an early warning signal for osteoporosis." (PMID 39170742, 2024).
periodontitis (1 paper, 2023). An acute or chronic inflammatory process that affects the tissues that surround and support the teeth. "In the future, changes in periodontal tissue should be observed by inducing periodontitis in TRPC3 and TRPC6 knockout animal models or by using TRPC3 and TRPC6 modulating drugs in a periodontitis animal model to clarify the functional role of TRPC3 and TRPC6 in periodontitis." (PMID 37653550, 2023). "Experiments using TRPC3 and TRPC6 knockout animal models or TRPC3 and TRPC6 modulating drugs should be performed to determine how increased TRPC3 and TRPC6 expression is related to the progression of periodontitis." (PMID 37653550, 2023). "TRPC3 expression in the PDL area was increased on days 7 and 28 during periodontitis induction, and interestingly, the expression in osteoblasts was not different from that of the control group." (PMID 37653550, 2023). "The expression of TRPC3 and TRPC6 was investigated in mice periodontal tissue during a 28-day periodontitis induction period." (PMID 37653550, 2023). "Although a previous study showed that the application of mechanical force induced TRPC6 activation in the orthodontic tooth movement model, this study is the first to observe TRPC3 and TRPC6 expression in the periodontitis model." (PMID 37653550, 2023). "In ligature-induced periodontitis mice, the alveolar bone and osteoid areas, the osteoclast number, and the expression of Runx2, OCN, TRPC3, and TRPC6 was evaluated by H&E staining, TRAP staining, and immunohistochemistry, respectively." (PMID 37653550, 2023). "This study evaluated the expression of TRPC3 and TRPC6 in periodontal tissue during periodontitis induction." (PMID 37653550, 2023). "Based on the results of previous studies and the expression of TRPC channels during osteoblast differentiation of PDL cells in this study, we focused on the expression of TRPC3 and TRPC6 during periodontitis progression, which was evaluated by immunohistochemical staining." (PMID 37653550, 2023). "This study observed an increase in the expression of TRPC3 and TRPC6 in PDL cells that were differentiating into osteoblasts and periodontitis-induced tissue but had a limitation in that the role of TRPC3 and TRPC6 in periodontitis could not be identified." (PMID 37653550, 2023).
pheochromocytoma (1 paper, 2020). "Validation and characterization of the sesquiterpene plant metabolite by complementary methods revealed an unexpected TRPC3-selective, PLC- and diacylglycerol-independent mode of action that was confirmed in rat pheochromocytoma cells that endogenously express TRPC3 and TRPC6." (PMID 31947602, 2020). "Although the neural origin of pheochromocytoma cells, including PC12, may explain the functional expression of TRPC3, the epinephrine-producing cells of the adrenal medulla in pigs do not express TRPC3." (PMID 31947602, 2020).
primary hyperparathyroidism (1 paper, 2024). Hyperfunction of the parathyroid glands resulting in the overproduction of parathyroid hormone. "Surgery samples from patients with healthy parathyroid glands and from patients suffering from primary hyperparathyroidism (pHPT) were investigated by immunohistochemistry using knockout-validated antibodies against TRPC3 and TRPC6." (PMID 38673977, 2024).
prostate tumours (1 paper, 2022). "The results of the bioluminescence imaging and tumour size measurements revealed that TRPC3 downregulation in prostate stromal cells accelerates growth of the newly formed subcutaneous prostate tumours." (PMID 35177596, 2022).
Rett syndrome (1 paper, 2020). A severe neurodevelopmental disorder affecting the central nervous system.
rhabdomyolysis (1 paper, 2023). Necrosis or disintegration of skeletal muscle often followed by myoglobinuria. "The authors of the study suggested that the production of ET-1 and the activation of TRPC3-dependent renal vasoconstriction play a critical role in the development of rhabdomyolysis-induced AKI." (PMID 37575481, 2023).
schizophrenia (1 paper, 2025). A major psychotic disorder characterized by abnormalities in the perception or expression of reality. "Multiple differentially expressed genes (KCNIP4, GRM3, PRKG1, NPY for inh-C, and TRPC3 for inh-CCK) were related to glutamate reception and calcium channel activity, indicating these processes are altered within inhibitory midbrain neurons in schizophrenia." (PMID 39397771, 2025).
serous ovarian cancer (1 paper, 2020). "Immunocytofluorescence analysis showed that the expression of TRPC3 in serous ovarian cancer tissue was higher than that in normal tissue." (PMID 32087757, 2020).
Spinocerebellar ataxia type 41 (1 paper, 2024). Spinocerebellar ataxia is characterized by progressive imbalance and gait ataxia with mild atrophy of the cerebellar vermis. "Previously, a rare TRPC3 variant (NM_001130698.2:c.2285G > A; p.Arg762His) (R762H) was identified in a patient with spinocerebellar ataxia type 41 (MIM#616410)." (PMID 38425503, 2024).
ventricular tachycardia (1 paper, 2020). A disorder characterized by an electrocardiographic finding of three or more consecutive complexes of ventricular origin with a rate greater than a certain threshold (100 or 120 beats per minute are commonly used). "TRPC3 overexpressing hearts were also more susceptible to ANG-II-stimulated arrhythmic events which included atrial or ventricular tachycardia." (PMID 33013458, 2020).
ZIKV infection (1 paper, 2024). "Conversely, no significant alterations were observed in the expression of TRPC1, TRPC3, TRPC5, or TRPC6 upon ZIKV infection." (PMID 39009885, 2024). "However, AC1903, a specific TRPC5 inhibitor, and Pyr3, an antagonist for TRPC3/C6, did not exhibit protective properties in our cell model for ZIKV infection." (PMID 39009885, 2024).